ATM (ATM serine/threonine kinase)
Diseases named in the same sentence as ATM in open-access papers (continued):
Sharing a sentence is not in itself a finding about the gene and the disease.
Immunodeficiency (79 papers, 2009 to 2026). Failure of the immune system to protect the body adequately from infection, due to the absence or insufficiency of some component process or substance. "The ATM variants are shown to worsen features of metabolic syndrome, including hypertension, and are associated to immune deficiency and CVD." (PMID 39972178, 2025). "In cases with mutations that greatly disrupt ATM protein synthesis, ataxia and immune dysfunction manifest in early childhood, while partially functional protein variants result in a more gradual disease progression." (PMID 41451872, 2025). "Mutations in the ATM gene contribute to ataxia capillaries (A-T), a rare neurodegenerative and immunodeficiency disorder characterized by cerebellar ataxia capillaris, immunodeficiency, radiosensitivity, and cancer susceptibility." (PMID 36325336, 2022). "Loss function of ATM is associated with the hypersensitivity to ionizing radiation, cancer susceptibility, immunodeficiency, and genomic instability." (PMID 33980813, 2021). "The respective effects of ATM protein loss or isolated loss of kinase activity on both the severity of immunodeficiency and the development of these atypical T cell expansions in human patients remains to be further studied in a larger patient cohort." (PMID 34248969, 2021). "A-T is a DNA repair disorder, caused by mutations in the Ataxia Telangiectasia Mutated (ATM) gene, leading to neurodegeneration with progressive ataxia, telangiectasias, predisposition to malignancies, sensitivity to radiation, and immunodeficiency." (PMID 31709473, 2020). "Through all these pathways, ATM helps in preventing neurodegeneration, immune deficiency, sterility, and cancer." (PMID 32858941, 2020). "Mutations in the ataxia telangiectasia mutated (ATM) gene cause ataxia telangiectasia (A-T) syndrome, a rare disease that exhibits cancer predisposition, neurodegeneration, immunodeficiency, and premature aging of the skin and hair." (PMID 29472706, 2018). "Individuals with mutations in both copies of the ATM gene suffer from increased susceptibility to ionizing radiation, predisposition to cancer, insulin resistance, immune deficiency, and premature aging." (PMID 29152614, 2017). "Mutations leading to immune deficiencies have been described that are associated with most members of the ATM–MRN machinery." (PMID 26455503, 2016). "Aside from immune deficiency secondary to AT, loss of ATM function could also hinder the control of the virus within B-cells, favoring lymphomagenesis in AT patients." (PMID 34183044, 2021). "ATM was originally identified in individuals with ataxia-telangiectasis (AT), an autosomal recessive disorder that manifests with progressive ataxia, telangiectasia, immunodeficiency, genomic instability, and cancer predisposition." (PMID 31781094, 2019). "Beside immune deficiency, ATM could also contribute to AT-associated EBV-related lymphoid malignancies by interfering with the B-cell intrinsic regulation of EBV persistence." (PMID 30662441, 2018). "Therefore, ATM deficiency affects the V(D)J recombination-induced DSBs preventing the production of antigen receptors, compromising T- and B-cell developments and causing severe immune deficiencies." (PMID 25247188, 2014). "Combined immunodeficiencies alongside syndromic characteristics were associated with pathogenic mutations in DOCK8, STAT3, WAS, ATM, and TBX1, which included an autosomal dominant STAT3 variant (c.1144C>T; p.Arg382Trp) and an X-linked WAS variant (c.271C>T)." (PMID 40806973, 2025). "The 8th key protein ATM plays a central role in responses to various forms of DNA damage, immunodeficiency, virus integration, virus replication and virus infection." (PMID 35390032, 2022). "Additional genetic defects in MTHFD1, RMRP, CORO1A, PNP, DOCK8, ATM, and BCL11B, among others also cause combined immunodeficiencies, which can be detected by low TREC copy number analysis." (PMID 29713328, 2018).
Immunodeficiency (continued). "Mutations in DNA repair genes, including ATM and NBS1 have been linked with immunodeficiencies in patients and furthermore immune deficiency is an important factor in causality of human inflammatory diseases such as inflammatory bowel disease (IBD)." (PMID 26544571, 2015). "A-T patients lack a functional ATM protein and exhibit wide array of systemic defects including immunodeficiency, cerebral degeneration, progressive ataxia, premature aging, increased incidence of lymphoid tumorigenesis and type-2 diabetes." (PMID 24957606, 2014). "Interestingly, Akt knockout mice show some similar phenotypic abnormalities to ATM-deficient mice, such as growth retardation, insulin resistance, hypersensitivity to gamma-irradiation, and immunodeficiency, indicating that ATM and Akt may be involved in the same signalling transduction pathway." (PMID 22481935, 2012). "Additionally, Lavin and Shiloh confirmed that ATM dysfunction not only contributes to genomic instability, but also results in profound immunological disturbances, explaining the immunodeficiency observed in patients in the present study." (PMID 41451872, 2025). "For 111 patients with suspected combined immunodeficiency, including SCID/AT, we analyzed T‐cell receptor excision circle (TREC) and sequenced 29 causative genes of SCID, including ATM, by ion semiconductor sequencing using multiplex polymerase chain reaction amplicons." (PMID 40457861, 2025). "Missense mutations, which involve amino acid substitutions that do not prevent ATM activity entirely, are linked to milder disease courses, with later onset of ataxia and less-pronounced immune deficiency." (PMID 41451872, 2025). "Collectively, the immunodeficiency manifestations—decreased IgA, reduced B lymphocytes, a slight increase in IgM, and significantly elevated AFP levels—support the diagnosis of A-T caused by novel frameshift mutations of the ATM gene in this Chinese family." (PMID 39678378, 2024). "In fact, the role of ATM is intriguing: ATM is associated with DDR signaling, the control of cellular redox balance and mitochondrial function, immunodeficiency, chronic lung disease, cancer predisposition, endocrine abnormalities, segmental premature aging, and radiation sensitivity." (PMID 37511215, 2023). "ATM involvement in the DDR can explain many pathological hallmarks of ataxia-telangiectasia, including a predisposition to cancer, hypersensitivity to ionizing radiation, immunodeficiency, and infertility." (PMID 35806485, 2022). "The possible mechanisms of autoimmunities in ATM deficiency were introduced either secondary to immunodeficiency or as an effect of the lack of ATM protein." (PMID 36544766, 2022). "ATM’s involvement in DDR clearly explains many pathological hallmarks of A-T disease including cancer predisposition, hypersensitivity to ionizing radiation, immunodeficiency, and infertility." (PMID 32858941, 2020). "One mechanism proposed to explain immunodeficiency has been immunoglobulin deficiency (both IgA and IgG2) but the role of ATM in innate immunity has not been investigated." (PMID 24957606, 2014). "Patients lacking functional ATM present multiple clinical features, such as progressive cerebellar ataxia, susceptibility to malignancies, variable immunodeficiency, hypersensitivity to IR, and increased incidence of metabolic diseases, indicating the critical role of ATM in genome stability." (PMID 35085551, 2022).
Immunodeficiency (continued). "Altogether, our patient had an onset of A-T syndrome at the age of 6 years with slow progression and a lack of basal ganglia manifestations, ruling out immunodeficiency, which may indicate that her mutations led to less severe neurodegenerative effects compared to other mutations in the ATM gene." (PMID 38882696, 2024). "In summary, DDR represented by phosphorylation of H2AX, ATM, and CHK2 is a highly sensitive tool to identify patients with AT that can be readily distinguished from patients with other combined immunodeficiencies." (PMID 34716846, 2022). "Sixty-four children were recalled for follow-up due to low TREC and/or KREC levels, and three patients with immunodeficiency (Artemis-SCID, ATM, and an as yet unclassified T cell lymphopenia/hypogammaglobulinemia) were identified." (PMID 27873105, 2017). "ATM, although not completely required, facilitates V(D)J recombination, providing a molecular explanation for the relatively mild immunodeficiency characteristic of A-T patients and Atm−/− mice." (PMID 32060399, 2020). "It has been hypothesized that the immunodeficiency phenotype and lymphocyte dysregulation-driven hyperinflammation due to the lack of ATM activity in A-T are contributory factors to interstitial pneumopathy and lung fibrosis." (PMID 36186632, 2022). "These in vivo results reveal new functional interplays between XRCC4 and PAXX, ATM and Xlf in mouse development and provide new insights into the understanding of the clinical manifestations of human XRCC4-deficient condition, in particular its absence of immune deficiency." (PMID 34519267, 2021).
colon carcinoma (78 papers, 2004 to 2025). "To examine the efficacy of anti-Gal-9 therapy in ATM-silenced tumors, we first established an ATM knockdown (KD) cancer cell line by transducing the murine CT26 colon cancer cells with lentiviruses encoding shRNA for ATM." (PMID 36778120, 2023). "ATM-silencing mutations or deletions have also been found in other types of tumors, such as lung adenocarcinoma and colon cancer." (PMID 34068084, 2021). "Given the significance of HITT in regulating ATM’s activity, we further investigated their association in vivo in human colon cancers." (PMID 32203529, 2020). "A reverse association between HITT and ATM activity was also detected in human colon cancer tissues." (PMID 32203529, 2020). "We demonstrate for the first time that Xn exerts its anticancer activity in models of colon cancer through activation of the ataxia telangiectasia mutated (ATM) pathway." (PMID 32290112, 2020). "We demonstrated for the first time that Xn exerts its anticancer activity in models of colon cancer by activating the ataxia telangiectasia mutated (ATM) pathway." (PMID 32290112, 2020). "The ATM c.3806A > G variant was identified in an early-onset BC patient (<50 years) with a strong BC, ovarian and colon cancer family history." (PMID 31811167, 2019). "ATM loss is attributed to aberrant splicing associated with intronic shortening in MSI positive colon-cancer cell lines." (PMID 24324828, 2013). "We also investigated if DCQ causes apoptosis, induces SSB and activates the ATM repair pathway in human colon cancer cells." (PMID 21078189, 2010). "We thus determined whether induction of ATM-associated DNA damage is the main trigger for baicalin-induced senescence in human colon cancer cells." (PMID 29732005, 2018). "Interestingly, a recent clinical study associated low ATM expression in colon cancer with poor clinical outcomes." (PMID 26257651, 2015). "As in colon cancer, immunotherapy proved to be effective in patients with alterations of mismatch repair gene alterations; we could hypothesize that ATM mutations could enhance the genomic instability of DNA and enhance the immunotherapy response in triple-negative BC patients." (PMID 34068084, 2021). "The ATM/AKT pathway is a compensatory mechanism to cope with the ROS accumulation induced by the inhibition of the Trx system in colon cancer." (PMID 39744566, 2025). "Loss of ATM expression is associated with poor survival in CRC and an increase in phosphorylated ATM protein levels has been observed in hypoxic colon cancer cells." (PMID 38137047, 2023). "In the current study, our data have disclosed that PXR protects liver and colon cancer cells from IR-induced DNA damage through ATF3-mediated ATM activation." (PMID 35372071, 2022). "LncRNA HITT (HIF1A inhibitor at translation level) directly interacts with ataxia-telangiectasia mutated (ATM) and suppresses homologous recombination repair in human colon cancer tissues." (PMID 36230902, 2022). "By contrast, genes with inhibited functions (shown in blue) were involved in apoptosis, movement disorders, motor dysfunction, seizure, colon cancer, ATM signaling, PI3K/AKT signaling, and neuronal cell death." (PMID 35743705, 2022). "Subsequently, the DDR pathway induced by the activation of ATM/ATR proteins is modulated in colon cancer cells." (PMID 32290112, 2020). "Proximal colon tumors showed higher mutation frequencies than distal tumors on TGFBR2 (30.0% vs 2.8%, P < 0.001), ATM (20.0% vs 2.8%, P = 0.020), BLM (25.0% vs 2.8%, P = 0.005), and PTEN (15.0% vs 1.4%, P = 0.032) genes." (PMID 31548566, 2019). "The difference in ATR, ATM and Chk1 expression pattern between rectal and colon cancer strength that of considering colon and rectum are distinctive organs rather than one common entity, at least at the molecular level." (PMID 29870526, 2018).
colon carcinoma (continued). "An increase in phosphorylated ATM levels in hypoxic HCT116 colon cancer cells was described, but the modulation of ATM expression by low oxygen tension and the sensitivity of expression to E2, in CRC was not investigated." (PMID 29137421, 2017). "For example, the telomerase-positive HCT116 colon cancer cell line used here harbors a mutation in MRE11, which impairs binding to NBS1 and Rad50 and suppresses ATM activation in response to replication stress." (PMID 27602331, 2016). "Recently, CGK733 has been shown to induce cell death in breast, lung, and colon carcinoma cells by modulating ATM, p21 (CIP1) and cyclin D1." (PMID 26259235, 2015). "Recent studies have reported that GANT61 triggers apoptosis via induction of DNA double strand breaks and activation of ATM-Chk2 DNA damage response in colon cancer cells." (PMID 25544756, 2015). "Three of the five patients with mutated ATM without a family history of GC had a family history of other cancers, including breast and colon cancer." (PMID 40446793, 2025). "Our notion that ATM appears in various isoforms in phendione-treated cells may likewise be a result of altered ATM RNA splicing that was observed in LB-100 treated colon cancer cells." (PMID 38570831, 2024). "On the other hand, because ATM can stimulate the differentiation of myofibroblastic cancer-associated fibroblasts, which promote suppressive TIME, ATM inhibition in fibroblasts can increase tumor-infiltrating CD8+ T cells and improve ICB therapy in mouse models of lung and colon cancers." (PMID 37174688, 2023). "This damage can be strong enough to induce checkpoint kinase 1 activation and G2/M arrest in colon cancer cells through the activation of the ataxia-telangiectasia mutated (ATM) protein kinase when DNA damage is not repaired." (PMID 34456713, 2021). "Since we found that PER1 was the most significant downregulated genes when PER2 expression is low, the process may be related ATM/CHK2 as reported in a human colon cancer cell line." (PMID 33810377, 2021). "Moreover, HITT expression is commonly decreased, whereas p-ATM levels are increased, in colon cancer tissues." (PMID 32203529, 2020). "In contrast, L-OHP-resistant colon cancer cells have low levels of ATM." (PMID 29963241, 2018). "It is also consistent with our finding that human breast and colon tumors with higher levels of activated ATM have poor prognosis: a higher level of activated ATM may indicate higher numbers of malignant cancer stem cells." (PMID 28337983, 2017). "Likewise, doxorubicin-treated breast, lung, and colon carcinoma cells undergo cellular senescence in vitro, which is characterized by a constitutively active ATM/ATR-dependent DNA damage response and the induction of p21." (PMID 21637851, 2011).